TNF (tumor necrosis factor)
Diseases named in the same sentence as TNF in open-access papers (continued):
Sharing a sentence is not in itself a finding about the gene and the disease.
lymphoma (continued). "This case suggests a potential relationship between immunosuppression with anti-TNFα medication, and increased risk for lymphoma, especially in patients with underlying rheumatologic disorders and especially in patients with suspected chronic refractory uveitis." (PMID 29954352, 2018). "The occurrence of LPD in RA patient with receiving immunosuppressive therapy is recognized as the “Immunodeficiency-associated LPDs” by the World Health Organization (WHO) and a possible link between TNF-α inhibitors treatment and increased risk of lymphoma has been suggested." (PMID 25694859, 2015). "These include a potential for myocarditis, and development of coronary artery abnormalities, ischemia and the risk of TB and cancer (mainly lymphomas in patients receiving etanercept) although the existence of a cause and effect relationship between anti-TNF use and lymphomas remains controversial." (PMID 23008735, 2012). "However, lymphoma risk appears to be higher in adult RA patients using TNF-inhibitors as compared to that of the general population, but appears to be similar or only slightly elevated when compared with a background RA population." (PMID 20546618, 2010). "Some early studies suggest that anti-TNF-α agents may increase the risk of malignancies, especially lymphoma." (PMID 20569501, 2010). "Also, some reports have suggested an increased risk of malignancies, especially lymphoma, in RA patients treated with anti-TNF-α therapies, but this has been refuted by several recent studies." (PMID 20569501, 2010). "In August of 2009, the FDA notified healthcare professionals that it has completed its analysis of TNF-alpha blocking agents and concluded that there is an increased risk of lymphoma and other cancers associated with the use of these drugs in children and adolescence." (PMID 20016776, 2009). "However, it cannot be overlooked that a simultaneous combined therapy with anti-TNF antibodies and thiopurines may increase the risk of lymphoma compared to monotherapy with thiopurines." (PMID 40564114, 2025). "The risk of lymphoma associated with anti-TNF agents remains unclear." (PMID 37206474, 2023). "However, considering the increased activity of EBV in RA patients, it was suspected that widely used methotrexate, with later introduced TNF alpha inhibitors, could also increase the risk of developing lymphoma." (PMID 37760816, 2023). "However, while these treatment strategies alleviated symptoms and induced and maintained remission in patients with IBD, several observational cohort studies have reported that patients receiving thiopurines, anti-TNF monotherapy, or a combination of both drugs were at risk of developing lymphoma." (PMID 37593734, 2023). "TNF- α and LT-α cytokine polymorphisms may affect autoimmune diseases such as rheumatoid arthritis, leukemia and lymphoma genesis by hinder DNA repair mechanisms or up-regulation of pro inflammatory and anti-apoptotic signals via nuclear transcription factor kappa B (NF-kB) pathway." (PMID 24171078, 2013). "Thus, it is critical to know the background rate of malignancy in children with JIA; without this data, there is no way of deciphering either a protective effect or increased risk of lymphoma development in children with JIA treated with TNF inhibitors, such as etanercept." (PMID 20712883, 2010). "It produces butyrate to suppress the TNF/TLR4/MyD88 signaling pathway and inhibit the NF-κB pathway in B cells, thus reducing TNF-associated intestinal inflammation and the incidence of lymphoma in Eμ-Myc mice." (PMID 41355959, 2026). "Caution is advised when considering the use of TNF-alpha inhibitors in patients with a history of lymphoma." (PMID 40893576, 2025). "Studies have demonstrated that estrogen modulates the expression of key cytokines, such as interleukin-6 and tumor necrosis factor-alpha, which contribute to tumor progression and immune evasion in some cancers, including lymphomas." (PMID 39926277, 2025).
lymphoma (continued). "Previous study showed high levels of IL-10, IL-6, IL-1β, and TNF-α in lymphoma patients except TNF-α in NHL patients." (PMID 40076681, 2025). "The decision to use this agent was due to this patient’s history of lymphoma, which limited the use of immunomodulators, anti-TNF medications, and ustekinumab." (PMID 39917029, 2025). "In contrast to IL-1β and FVIII, TNF-α and P-selectin were increased in lymphomas and DLBCL with thrombosis." (PMID 40076681, 2025). "First, the systemic inflammatory cytokines produced by lymphoma cells, such as IL-4, IL-5, and TNF-α, can increase pruritus and facilitate the development of pruritic nodules." (PMID 39911286, 2025). "Co-culture assays with lymph node or spleen cells from vaccinated mice show enhanced tumor cell killing and increased IFN-γ and TNF-α levels, indicating lymphoma-specific immunity." (PMID 41360751, 2025). "The issue of latency in diagnoses of lymphoma shortly after commencing anti-TNF-α treatment highlights the need for washout periods." (PMID 39064585, 2024). "Overall, those studies highlight the efficacy of anti-TNF-α therapies in improving outcomes in RA, albeit with some incidence of lymphoma observed that requires careful long-term monitoring." (PMID 39064585, 2024). "A greater risk has also been reported for lymphomas and skin cancer in older patients with IBD, particularly if they receive treatment with immunomodulators or anti-TNF drugs." (PMID 39768503, 2024). "It has also been suggested that intestinal Eubacterium can inhibit lymphoma development by decreasing TNF-a levels and thereby reducing the inflammatory response." (PMID 39164740, 2024). "However, because the blockade of TNF-α also plays a crucial role in modulating immune responses against B cell lymphomas, the long-term use of the agents raises concerns regarding the associated potential risk of developing lymphoma, a diverse group of malignancies arising from lymphocytes." (PMID 39064585, 2024). "The anti-TNF-α mechanism of action inhibits apoptosis and thus enables the proliferation of neoplastic cells, including lymphomas." (PMID 38673824, 2024). "Our findings revealed that TFAB002s effectively lysed lymphoma B cells while demonstrating moderate increases in key cytokines such as IL-2, TNF-α, and IFN-γ." (PMID 39321199, 2024). "Cases of lymphoma have also been reported in HS patients receiving systemic therapy with TNF-α inhibitors." (PMID 39046819, 2024). "The presence of LPS in the microbiota of lymphoma patients interacted with TNF signaling and enhanced the NF-κB pathway through MyD88-dependent TLR4 signaling, leading to increased survival and proliferation of intestinal B cells." (PMID 38415259, 2024). "Empirical evidence suggests that butyrate-producing Eubacterium inhibit lymphoma development by attenuating the TNF-activated TLR4/MyD88/NF-κB signaling cascade." (PMID 38774867, 2024). "In case reports on HS patients who developed lymphoma under TNF- α inhibition, only the occurrence of NHL, particularly two cases of B-cell lymphoma, was reported." (PMID 39046819, 2024). "The influence of RA treatment with methotrexate (MTX) or TNF blockers and other biological treatments on the risk of developing EBV-associated complications, such as lymphomas, is still debatable." (PMID 37760816, 2023). "We found that most IBD patients had been treated with thiopurines and/or anti-TNF agents before lymphoma diagnosis, and these patients were younger at diagnosis of lymphoma than those not treated with these drugs." (PMID 36765708, 2023). "In fact, there is strong evidence that anti-TNF-alpha therapy can lead to cases of lymphomas and various malignancies." (PMID 37096248, 2023). "Eighteen patients (35%) were treated with combination therapy of thiopurines and anti-TNF during a median of 22 months (IQR 6–37 months) before the diagnosis of lymphoma." (PMID 36765708, 2023).
lymphoma (continued). "In a subsequent study, the same group of authors synthesized ten new (+)-UA imidazolium salts, which were evaluated for the in vitro anti-inflammatory potential of TNF-α and IL-1β on the LPS-stimulated human lymphoma U937 cell line." (PMID 37109575, 2023). "The only compelling deviations from this pattern were more than threefold increased risk of lymphomas in patients with IBD with concomitant PSC and in those receiving combination immunosuppressive therapy with anti-TNF-α therapy and thiopurines." (PMID 37142293, 2023). "On the contrary, treatment with Eubacterium rectum reduced TNF levels and lymphoma incidence rate in sensitized Eμ-Myc mice." (PMID 37190210, 2023). "In our series, only one patient was on treatment with ustekinumab at the onset of lymphoma but had been treated previously with combination therapy of thiopurines and anti-TNF." (PMID 36765708, 2023). "One study found that anti-TNF inhibits Natural Killer cell activity and has a detrimental effect on in vitro anti-lymphoma activity." (PMID 37206474, 2023). "One published series described 48 cases of malignancy reported to the FDA in children on a TNF inhibitor, half of which were lymphomas." (PMID 37554981, 2023). "Stimulation with SARS-CoV-2-specific peptides revealed that myeloma patients had an increased percentage of Tfh cells reacting to these peptides with the production of IFN and TNF compared to lymphoma patients." (PMID 37187728, 2023). "A second, subsequent study demonstrated, in an in vitro lymphoma model, how Epstein-Barr virus-driven lymphomatoid transformation was amplified by both anti-TNF and 6-mercaptopurine." (PMID 37206474, 2023). "In the Swiss IBD cohort of 3119 patients, increased lymphoma rates with anti-TNF were found in both CD (HR 3.26, 95% CI: 1.31–8.10) and UC patients (HR 25.25, 95% CI: 2.94–217.26)." (PMID 36983432, 2023). "Two experimental investigations back up the idea that anti-TNF, either alone or in combination with thiopurines, contributes to the development of lymphomas." (PMID 37206474, 2023). "Anti-TNF drugs were administered during a median of 32 months (IQR 12–63 months) before diagnosis of lymphoma." (PMID 36765708, 2023). "The risks of lymphoma/HSTCL were also observed to be significantly greater when patients received a combination therapy of anti-TNF and thiopurine." (PMID 36983432, 2023). "We found that around 60% of patients had been treated with immunosuppressive drugs and/or anti-TNF before the diagnosis of lymphoma." (PMID 36765708, 2023). "Among signaling pathways, we found cytokine-cytokine receptor interaction, NF-κB signaling pathway, and TNF signaling pathway was enriched in all three lymphomas." (PMID 35452413, 2022). "TNFAIP3, also known as A20, represents a tumor suppressor gene in lymphomas that synergistically attenuates NF-κB signaling induced by tumor necrosis factor (TNF) and TLR signal transduction." (PMID 35937947, 2022). "To further define the role of Ayu_ND activated DC derived TNF-α mediated antitumor effects against lymphoma cells in vitro we performed antibody neutralization experiments." (PMID 35444547, 2022). "The IFN-γ and TNF-α levels of patients with lymphoma were higher than those of healthy controls (P<0.05)." (PMID 35432366, 2022). "The most mentioned anti-TNF agents are etanercept and infliximab related to the development of lymphoma in AS patients in the literature." (PMID 36128217, 2022). "A recent study found that IL6, IL8, TNF, and other cytokines expression varies in lymphoma patients (both HL and NHL) and health populations." (PMID 35452413, 2022). "Gelatin has also been shown to regulate the production and secretion of IL-6 and TNFα in differentiated U937 lymphoma cells." (PMID 34821368, 2021). "Comparable cytokine levels (granulocyte macrophage colony-stimulating factor GM-CSF, interferon [IFN]-γ, IL-2, and tumor necrosis factor alpha [TNF-α]) were detected in all CAR T cell samples upon exposure to CD19-positive lymphoma cells." (PMID 33575430, 2021).
lymphoma (continued). "The identification of three cytokines, IFN‐γ, TNF‐α, and IL‐10, secreted from the lymphoma cell lines upon Con A stimulation further demonstrated the potential of the proposed assay for clinical diagnosis." (PMID 34114369, 2021). "These accumulating data from large national registries, therefore, call into question the earlier data suggesting a link between TNF inhibitor use and the development of lymphoma." (PMID 33535498, 2021). "The most commonly reported cases of lymphoma associated with IBD were hepatosplenic T cell lymphoma and non-Hodgkin’s B cell lymphoma, which often developed following the use of TNF-α antagonists and immunosuppressants." (PMID 33810197, 2021). "The cytokines IL-4, IL-6, IL-10 and TNFα are produced by T cells, but often also by activated lymphoma cells or macrophages." (PMID 32899476, 2020). "Serum tumor necrosis factor-α (TNF-α) appears to have a limited value as a tumour marker in dogs with lymphoma, being detectable in only 12% of affected patients." (PMID 30987001, 2019). "A recent study showed that tumor cell death following TNF production by CD4+ TILs during ACT required co-treatment with chemotherapeutic agents in murine models of lymphoma as well as colorectal and mammary carcinoma." (PMID 31417576, 2019). "Although TNF-α has anti-apoptotic signals via the nuclear transcription factor (NF)-κB pathway, it influences lymphoma development through pro-inflammatory cytokines such as IL-1β, IL-6, and IL-8." (PMID 30814315, 2019). "We previously showed that TNF-α and circadian gene modulation alters the expression of clock genes and triggers phenotypic changes in lymphoma cells." (PMID 31311174, 2019). "Our result showed high levels of IL-10, IL-6, IL-1β, and TNF-α in lymphoma patients compared with control." (PMID 30814315, 2019). "On the other hand, patients with lymphoma exhibited a loss of functional EBV-specific CD4+ T cells, as demonstrated by TNF-α+ (p = 0.008); IFN-γ+ (p = 0.025); and IL-2+ (p = 0.009) counts." (PMID 30337929, 2018). "TNF and circadian gene modulation impacted on clock genes expression and triggered phenotypic changes in lymphoma cells, suggesting a crucial involvement of core-clock elements and TNF in the physiopathological mechanisms hastening malignancy." (PMID 30065253, 2018). "A study of 343 lymphomas which occurred between 1964 and 1995 in RA patients from Sweden before TNF blockers were used demonstrated that, although most lymphomas were B cell derived, only 12% contained the EBV genome." (PMID 28199343, 2017). "Corroborating our findings, a lymphoma study also reported upregulation of IL-8 in FRCs after TNF-α treatment." (PMID 28261205, 2017). "Concerns about a possible correlation between TNF blockade and cancer first arose from postmarketing reports of 26 cases of lymphoma among patients treated with etanercept and infliximab." (PMID 28717771, 2017). "The cytokine TNF-α and metabolic profiling by gas chromatography have been evaluated as biomarkers of lymphoma." (PMID 27747218, 2016). "In lymphoma and myelogenous leukemia cells, suppression of TNF and another proinflammatory cytokine interleukin 1 (IL-1) were shown to downregulate the expression of active NF-κB and consequently inhibit tumor growth." (PMID 27887635, 2016). "In presence of TNF-α, healthy bone marrow MSCs have been shown to possess similar effects on monocytes and macrophages recruitment as lymphoma-derived MSCs, thus contributing to tumor growth." (PMID 27630452, 2016). "The team of Yufang Shi noticed TNFα-pretreated BM-MSCs mimicked lymphomas-MSCs in their chemokine production profile and ability to promote tumorigenesis of lymphoma, melanoma, and breast carcinoma." (PMID 27090786, 2016). "These analyses showed that the most common haplotype, C-G-G-A of TNF/LTA, had an increased risk of NK/T lymphoma (OR = 1.52, 95%CI = 1.13 ~ 2.04, P < 0.01), compared to carriers of the non-CGGA haplotype." (PMID 26108796, 2015).
lymphoma (continued). "Stimulated Vγ9Vδ2 T cells produce cytokines such as interferon-γ (IFN-γ) and tumor necrosis factor-α (TNF-α) and exhibit specific cytotoxicity against various tumor cells, including lymphoma and myeloma cell lines." (PMID 25686210, 2015). "It was reported that the administration of a conventional chemotherapeutic agent, such as cyclophosphamide or DOX, in combination with TNF-α, enhanced the antitumour effects against large established tumours in a murine lymphoma model." (PMID 25887995, 2015). "It has been postulated that lymphoma cells can produce certain cytokines such as tumor necrosis factor (TNF) α, platelet-derived growth factor (PDGF), and transforming growth factor (TGF) β, among others." (PMID 25984371, 2015). "As for anti-tumor necrosis factor (TNF) therapy, the association between anti-TNF therapy and malignant lymphoma was also unclear." (PMID 24721419, 2014). "We also apply these methods to a set of 64 cases of lymphoma occurring after anti TNF- α treatment from the French pharmacovigilance." (PMID 24490673, 2014). "An application to reported lymphoma after anti TNF- α treatment from the French pharmacovigilance is presented." (PMID 24490673, 2014). "In 2009, the FDA required box warnings on the labels of TNF blocker medications to alert patients that lymphoma and other malignancies, some fatal, have been reported in children and adolescent patients treated with TNF blockers." (PMID 24225257, 2013). "A polymorphism in the promoter region of the tumor necrosis factor (TNF)-α gene is one of several genetic changes involved in the development of lymphoma." (PMID 24265629, 2013). "It is difficult to assess the contribution of anti-TNFα therapy to developing lymphoma, as patients with severe RA are the same patients on anti-TNFα therapy." (PMID 23320919, 2013). "Tumor necrosis factor-α (TNF-α) and lymphtoxin-α (LT-α) are appropriate candidate genes for study of lymphoma and leukemogeneis because they code important immunoregulatory cytokines which are critical mediators of inflammation and apoptosis." (PMID 24171078, 2013). "Compared to lymphoma or solid tumors (n = 20), acute leukemia subjects (n = 15) displayed significantly higher concentrations (P<0.05) of IL-6, IL-8, IL-10, and TNF-α and lower levels of pro-LL-37 (P<0.001)." (PMID 23741421, 2013). "As α-tocopherol addition significantly reduced apoptosis induced by TNF-α, 7-ketocholesterol or nicotine in lymphoma or pulmonary epithelial cells, it was suggested that the protective role of the vitamin was a result of its anti-oxidative properties." (PMID 22590613, 2012). "This is relevant since all the lymphoma cases identified by the FDA in children with IBD on an anti-TNF mAb were also treated with the thiopurines, 6-MP or azathioprine." (PMID 20712883, 2010). "A total of 124 prior malignancies were found in 122 patients: 6 lymphomas (DMARDs: 2, anti-TNFα: 4), and 118 solid tumors (DMARDs: 54, anakinra: 9, anti-TNFα: 55)]." (PMID 20064207, 2010). "Conflicting reports have appeared in the literature regarding the influence of TNF inhibitors on rates of lymphomas and solid malignancies in adults." (PMID 20546618, 2010). "Taken together, such data provide reliable arguments to investigate a potential EBV reactivation during MTX and/or TNFα antagonist therapy as a possible first step of lymphoma induction." (PMID 19470150, 2009). "Recent concerns about possible treatment effects and lymphoma have focused on anti-TNF drugs because of their profound immunoregulatory effect." (PMID 19470150, 2009). "Because long-term experience with anti-TNF therapy is limited, the potential long-term risks, particularly of developing lymphomas, remains an issue." (PMID 19019215, 2008). "In conclusion, our study highlights an increased risk of both lymphoma and CRC in IBD patients, particularly among those treated with immunomodulatory therapy—whether as monotherapy or in combination with anti-TNFα agents." (PMID 40361323, 2025).